PSAPL1 (prosaposin like 1)
Description:
May activate the lysosomal degradation of sphingolipids.
Tractability: Antibody: UniProt places it where antibodies can reach, with high confidence; UniProt predicts a signal peptide or a membrane-spanning region; its Gene Ontology location is reachable by antibodies, with medium confidence.
Gene: Protein-coding gene on chromosome 4 (7,430,285 to 7,434,930, reverse strand). Ensembl gene ENSG00000178597.
Subcellular location: Secreted
Subcellular location (Human Protein Atlas): Cytosol; Predicted to be secreted
Gene Ontology:
Biological process: adenylate cyclase-inhibiting G protein-coupled receptor signaling pathway; epithelial cell differentiation involved in prostate gland development; prostate gland growth; regulation of lipid metabolic process; lipid metabolic process; sphingolipid metabolic process
Cellular component: cytosol; cytoplasm; extracellular region; lysosome
Genetic constraint (gnomAD): Missense variants: 814 observed, 678.97 expected, observed/expected ratio (o/e) 1.2, 90% interval 1.13 to 1.27. Synonymous variants: 351 observed, 284.8 expected, observed/expected ratio (o/e) 1.23, 90% interval 1.13 to 1.35.
Homologues: Orthologues: chimpanzee PSAPL1 (99% identical), macaque PSAPL1 (93% identical), rat Psapl1 (67% identical), mouse Psapl1 (66% identical), rabbit PSAPL1 (63% identical), pig PSAPL1 (61% identical), Drosophila melanogaster Sap-r (22% identical), Caenorhabditis elegans spp-10 (15% identical), zebrafish sftpba (12% identical), zebrafish sftpbb (11% identical). Paralogues in human: PSAP (44% identical), SFTPB (16% identical).
Diseases named in the same sentence as PSAPL1 in open-access papers:
PSAPL1 is named in the same sentence as 7 diseases in open-access papers, as found by Europe PMC text mining. Sharing a sentence is not in itself a finding about the gene and the disease. The quoted sentences say what the papers report.
atopic dermatitis (1 paper, 2022). "A clinical study identified PSAPL1 genes to be enriched in the patients with face and neck atopic dermatitis(AD), suggesting that innate immune system is potentially associated with the pathophysiology of face and neck AD." (PMID 35721061, 2022).
breast carcinoma (1 paper, 2022). "PSAPL1 was associated with breast cancer grade and involved in the epithelial cell differentiation pathways and the sphingolipid metabolic process." (PMID 35721061, 2022).
gastric cancer (1 paper, 2015). A primary or metastatic malignant neoplasm involving the stomach. "In addition, we discovered some novel genes, such as TMEM184A, PSAPL1, KIAA1199, CLRN3 and FNDC1, which have not been reported in gastric cancer previously, and their roles in cancer remain unknown." (PMID 25928635, 2015).
hepatocellular carcinoma (1 paper, 2023). A malignant tumor that arises from hepatocytes. "There was some literature about the oncogenic role of PSAPL1 in various solid cancers, including GC, BC, hepatocellular carcinoma." (PMID 37404760, 2023).
tumor (1 paper, 2025). "PSAPL1 is also linked to pathways involved in extracellular matrix organization and cell adhesion, which are important in tumor progression." (PMID 41244835, 2025). "Differentially expressed genes such as FAP, SERPINH1, and the newly reported PSAPL1 are involved in tumor progression, extracellular matrix remodeling, and immune response modulation." (PMID 41244835, 2025). "Notably, genes such as FAP, SERPINH1, and PSAPL1 have emerged as promising biomarker candidates due to their significant upregulation in GC tissues and their functional relevance in tumor progression, extracellular matrix remodeling, and immune evasion." (PMID 41244835, 2025).
PSAPL1 also shares sentences with these, for which no sentence is quoted: cancer (1 paper); leishmaniasis (1).